GASK1A (golgi associated kinase 1A)
Synonyms: C3orf41; FAM198A; DKFZP434B172
Tractability: Antibody: UniProt places it where antibodies can reach, with high confidence; UniProt predicts a signal peptide or a membrane-spanning region; its Gene Ontology location is reachable by antibodies, with medium confidence.
Gene: Protein-coding gene on chromosome 3 (42,979,087 to 43,067,898, forward strand). Ensembl gene ENSG00000144649.
Subcellular location: Secreted; Endoplasmic reticulum; Golgi apparatus; Membrane, caveola
Subcellular location (Human Protein Atlas): Vesicles; Predicted to be secreted
Gene Ontology:
Cellular component: endoplasmic reticulum; extracellular region; Golgi apparatus; caveola
Genetic constraint (gnomAD): Loss-of-function variants: 43 observed, 41.53 expected, observed/expected ratio (o/e) 1.04, 90% interval 0.81 to 1.34. The upper end of that interval is the gene's LOEUF score, 1.34, which puts it in group 5 of 6, group 1 being the genes least tolerant of losing a copy. Missense variants: 656 observed, 738.15 expected, observed/expected ratio (o/e) 0.89, 90% interval 0.83 to 0.95. Synonymous variants: 309 observed, 308.87 expected, observed/expected ratio (o/e) 1, 90% interval 0.91 to 1.1.
Homologues: Orthologues: chimpanzee GASK1A (98% identical), macaque GASK1A (94% identical), dog GASK1A (77% identical), rabbit GASK1A (71% identical), rat Gask1a (69% identical), mouse Gask1a (69% identical), guinea pig GASK1A (68% identical), tropical clawed frog gask1a (43% identical), zebrafish gask1a (37% identical). Paralogues in human: GASK1B (28% identical).
Diseases named in the same sentence as GASK1A in open-access papers:
GASK1A is named in the same sentence as 2 diseases in open-access papers, as found by Europe PMC text mining. Sharing a sentence is not in itself a finding about the gene and the disease. The quoted sentences say what the papers report.
tumor (2 papers, 2018 to 2023). "As a secretory protein kinase, GASK1A is expressed in basal epithelial cells, which is not only related to the occurrence and development of tumors but also may cause chemotherapy resistance in some tumor patients." (PMID 36816364, 2023).
GASK1A also shares sentences with these, for which no sentence is quoted: psoriasis (1 paper).